MSI1 (musashi RNA binding protein 1)
Diseases named in the same sentence as MSI1 in open-access papers (continued):
Sharing a sentence is not in itself a finding about the gene and the disease.
cancer (continued). "Regarding MSI1 was found highly expressed in human central nervous system and considered as an essential marker for neural stem cells or progenitor cells, accumulated studies have indicated MSI1 enriches the population of cancer stem cells." (PMID 27285760, 2016). "While mycobacterial infection was previously shown to induce TLR2-NOTCH1-PI3K-mTOR-NF-κB pathway to regulate immune responses, different cancer studies have implicated NOTCH3-dependent MSI1 expression and MSI1-dependent NOTCH activation." (PMID 27532872, 2016). "Stem cell marker, Musashi-1 (MSI1) is over-expressed in many cancer types; however the molecular mechanisms involved in MSI1 over-expression are not well understood." (PMID 25940441, 2015). "Because of the importance of Musashi family proteins in stem and cancer cell proliferation, we sought to identify a small molecule inhibitor of MSI1 RNA-binding activity." (PMID 24935936, 2014). "All of these data are in accordance with each other and support the idea that Msi1 is a tumor promoter in human cancers." (PMID 25362645, 2014). "In malignant tissues, Msi1 is highly expressed in gastric, gallbladder, colorectal, endometrial and lung cancer." (PMID 23715514, 2013). "A genome-wide analysis of Msi1 targets revealed >60 additional mRNA targets, many of which were related to cancer progression." (PMID 23715514, 2013). "MSI1-KD in adenocarcinoma cells results in tumor growth arrest in xenografts, reduced cancer cell proliferation, and increased apoptosis." (PMID 22428049, 2012). "Knowledge about the downstream target genes of MSI1 will shed light on the mechanism by which these proteins promote cancer cell progression." (PMID 22428049, 2012). "We believe that the identification of additional Msi1 direct target genes is necessary to better understand the function of this RNA binding protein in cancer cells." (PMID 18826648, 2008). "The RBP MSI1 plays a pivotal role in promoting therapeutic resistance in cancer." (PMID 40271197, 2025). "Musashi RNA-binding protein 1 (MSI-1) has a role in enhancing therapeutic resistance in cancer." (PMID 37631029, 2023). "ALDH1, CD133, CD44, Lgr5, Msi-1, and EphB1 are markers of cancer stemness." (PMID 36797277, 2023). "In addition, oleic acid can also influence cancer progression by upregulating MSI-1 expression levels to affect cell division." (PMID 37631029, 2023). "As MSI1 is well-known for stemness promotion in cancer cells as well as mesenchymal stem cells, upregulation of MSI1 in hAFSCs 3D spheroid cultures could indicate increased stemness potential when compared to 2D cultures." (PMID 36834995, 2023). "To examine whether the crude extract and 1′-O-methyl-averantin inhibit expression of cancer stemness markers in CSC221 cells, we measured expression of mRNA encoding ALDH1, CD133, CD44, Lgr5, Msi-1, and EphB1." (PMID 36797277, 2023). "Our present data revealed for the first time that peptidic disruption to the MSI1/AGO2 complex known for promoting cancer stemness and progression could lead to encouraging therapeutic efficacy at both in vitro and in vivo levels." (PMID 35158774, 2022). "Thus, target analysis indicated that miR-147 or pri-miR-147 exhibited potential interactions with MSI1, NF-κB p50, and KIAA1199, which are associated with the cancer signaling pathway." (PMID 36291177, 2022). "More recently, accumulating reports correlated MSI1 to stemness maintenance in breast and glioma cancer stem cells by downregulating proteasome expression, or by enhancing tumor invasion and migration to regulate cancer radioresistance." (PMID 35158774, 2022). "This discrepancy between bulk RNA–Seq and IHC data could result from a minor presence of MSI1+ cancer stem cells (CSCs) in these tumors or a potential cross–reactivity of the MSI1–directed antibodies with MSI2." (PMID 34062997, 2021). "MSI1 expression has been shown to promote cancer cell proliferation in a variety of malignancies." (PMID 34587981, 2021).
cancer (continued). "We thus assume that both cancer stem and normal cancer cells are changed by the MSI-1 knockdown." (PMID 34291358, 2021). "Our data are in line with previous reports that cancers with MSH6 germline variants often display low or absent MSI1,56." (PMID 34145315, 2021). "MSI1 has a crucial role in stem cell and cancer stem cell proliferation." (PMID 33541259, 2021). "Moreover, higher amount of MSI1 in those cell lines seems due to the reduced amount of miR-125b, which is responsible for epithelial features of those kinds of cancer cells." (PMID 33541259, 2021). "Finally, it is worth discussing the effect of MSI-1 knockdown on cancer stem cells versus the general cancer cell population." (PMID 34291358, 2021). "From this point of view, MSI1 solidifies its proposed role as a promising target candidate for cancer therapy, potentially as part of a combination therapy in a set of strategies, including differentiation therapy, Notch/Wnt antagonists and CDK or PARP inhibitors." (PMID 34062997, 2021). "The RNA–binding protein Musashi–1 (MSI1) promotes stemness during development and cancer." (PMID 34062997, 2021). "Along with this idea, MSI1/AGO2 binding could also negatively regulate the stability of another subset of mRNA targets related to apoptosis (group 2) to ensure cancer cell survival." (PMID 31903115, 2020). "Additionally, MSI1 maintains cancer stem cell phenotype as a consequence of stimulating Notch signaling due to downregulation of 26s proteasome activity." (PMID 32448364, 2020). "In this study, we aim to identify small molecule inhibitors of MSI1–mRNA interactions, which could block the growth of cancer cells with high levels of MSI1." (PMID 32784494, 2020). "Novel small molecule inhibitors may be used in the future for treating patients with high MSI1 expression, while also serving as a tool to elucidate MSI1′s role in cancer initiation and progression." (PMID 32784494, 2020). "Furthermore, silencing of MSI1 increases DNA damages in cancer cells treated with ionizing radiation through reduction in frequency of non-homologous end-joining (NHEJ) repair." (PMID 32448364, 2020). "MSI1 is overexpressed in a wide variety of cancers; although it’s specific function in tumorigenesis is largely unknown." (PMID 32784494, 2020). "Genome sequencing data in most of cancer tissues compared with normal tissues have shown that MSI1 was not mutated significantly." (PMID 32448364, 2020). "MSI1 is a main therapeutic target because it impacts a broad group of cancers." (PMID 32448364, 2020). "Different factors which stabilize MSI1 could enhance the cancer progress and drug resistance of cancer cells." (PMID 32448364, 2020). "In drug resistance pathway, MSI1 is effective in protection of cancer cells form apoptosis." (PMID 32448364, 2020). "MSI1 is a regulator of cancer stem cell functions by influencing RNA turnover." (PMID 32408494, 2020). "Several studies reported MSI1 re-expression or upregulation in various cancers." (PMID 33291443, 2020). "Increasing evidence points to the role of MSI1 in tumorigenesis and cancer proliferation." (PMID 31903115, 2020). "Some small molecules with inhibition of MSI1 function could facilitate to stop cancer cell proliferation and tumor progression." (PMID 32448364, 2020). "The crucial function of MSI1 in the maintenance of stem cell self-renewal also suggests its potential role in oncogenesis when dysregulated or aberrantly reactivated as the undifferentiated stem cell state is an indispensable feature of cancer." (PMID 31824472, 2019). "ALDH-1, CD133, CD44, Lgr-5, and Msi-1 are markers for the acquisition of cancer stemness." (PMID 28862656, 2017). "In order to understand the clinical relevance of our study, we used PrognoScan, a database used to correlate gene expression with patient prognosis, to determine the correlation between MSI1 expression with overall survival in patients with a variety of cancer types." (PMID 25940441, 2015).
cancer (continued). "MSI1 also promotes proliferation of numerous cancers of the brain and epithelial tissues." (PMID 24935936, 2014). "Thus, transcriptional analysis of D5E2 has the potential to accelerate the elucidation of Msi1-mediated NS/PC and cancer stem cell maintenance." (PMID 21486496, 2011). "In summary, our data suggest that Msi1 modulates proliferation of cancer cells." (PMID 18826648, 2008). "Msi1 knockdown reduced the ability of Daoy cells to form colonies in soft agar by 3 to 4-fold thus indicating that Msi1 promoted cell proliferation in these cancer cells and, consequently, that might play a role in tumor growth." (PMID 18826648, 2008). "We performed a shRNA mediated knockdown of Msi1 in Daoy and found that cancer cells expressing low levels of Msi1 were less clonogenic (proliferation assay), more differentiated (higher βIII Tubulin expression) and, possibly, more apoptotic (lower Bcl2 expression)." (PMID 18826648, 2008). "To determine if Msi1 might play a role in Daoy cancer cell proliferation, we measured the levels of MSI1 mRNA in Daoy neurosphere cultures by quantitative RT-PCR." (PMID 18826648, 2008). "We propose that Msi1 may maintain a pool of cancer cells with deregulated proliferative capabilities which may possibly serve as a source for future tumorigenic events." (PMID 18826648, 2008). "As Msi1 expression was elevated in Daoy neurospheres, we asked if Msi1 may promote expansion of cancer cells." (PMID 18826648, 2008). "As a member of RNA-binding protein that is abundant in the central nervous system, MSI1 has been shown to function as a predominantly functional marker by governing cell fate decision, differentiation, maintenance of stemness for progenitor neural stem cells, and tumorigenesis for cancer cells." (PMID 35158774, 2022). "Finally, combined use of MSI-1 silencing and irradiation reduced cancer cell survival." (PMID 34291358, 2021). "Here, we discuss functions and mechanisms directed by MSI1 in stemness and signaling, highlight its disturbed expression as well as prognostic value in solid cancers and summarize recent literature on promising targeting approaches with prospects in cancer therapy." (PMID 34062997, 2021). "This specific expression pattern together with its de–regulation and functional role in a set of human cancers puts MSI1 in row with other bona fide oncofetal RBPs such as IGF2BP1 and 3, LIN28B or MEX proteins, representing diagnostic markers with therapeutic potential for cancer treatment." (PMID 34062997, 2021). "Notably, in these cancers, MSI1 expression shows no striking association with patient survival, suggesting that elevated MSI1 expression is a conserved predictor of poor patient outcome in indicated cancers." (PMID 34062997, 2021). "However, how MSI1 expression is controlled in cancer remains largely elusive." (PMID 34062997, 2021). "Prospectively, MSI1–directed post–transcriptional control of gene expression could become even more complex involving RNA modifications, such as m6A (N6–methyladenosine), becoming more critical for cancer development." (PMID 34062997, 2021). "Considering the important role of MSI1 in DNA repair, resistance to chemotherapy, and spread of cancer through normal tissues, MSI1 targeting using different approaches may have the potential application as a reliable strategy for improvement of cancer treatment." (PMID 32448364, 2020). "In addition to its usefulness as a cancer biomarker, Msi1 may serve as a potential therapeutic target." (PMID 23715514, 2013).
cancer (continued). "Since neurosphere cultures can be enriched in tumor re-initiating cells and Msi1 is a stem cell marker with a role in cell cycle progression, the higher level of Msi1 detected in neurospheres indicated that Msi1 may contribute to Daoy cancer cell proliferation." (PMID 18826648, 2008). "Taken together, our results indicate that these three stem-cell-abundant proteins (Nanog, NS and Msi1 have roles in the carcinogenesis of cervical epithelial cells and regulate the cell differentiation, proliferation and asymmetric division, and maintain cancer cell pluripotency." (PMID 18419830, 2008). "Taken together, our data suggest that Msi1 may contribute to the proliferation of cancer cells." (PMID 18826648, 2008). "We thus propose that, by hijacking normal cell signaling pathways, Msi1 may sustain cancer cells." (PMID 18826648, 2008). "We demonstrate this approach by designing inhibitors of Musashi proteins MSI1 and MSI2, key regulators of mRNA stability and translation that are upregulated in many cancers." (PMID 36711552, 2023). "MSI1 activates the NOTCH and WNT pathways and consequently increases the cell proliferation and keeps the stemness status of cancer cells." (PMID 37607966, 2023). "Circ_0032833 downregulated the expression of Musashi1 (MSI1), which promoted drug resistance in cancer by sponging miR‐125‐5p." (PMID 36645225, 2023). "EL001672 and 1′-O-methyl-averantin suppresses the cancer stemness markers such as ALDH1, CD44, CD133, Lgr-5, Msi-1 and EphB1." (PMID 36797277, 2023). "RRA analysis further identify a set of MSI1-bound genes in G3 MB, including TMEM33, SFNX and HIPK1, as cancer-selective downstream targets for therapeutic drug targeting (i.e., not bound in NSC)." (PMID 36473869, 2022). "Previously, the ability of MSI1 to shuttle into cytosol was revealed, where it functioned to manipulate mRNA stability via its cytosolic binding partner AGO2 thereby promoting cancer progression." (PMID 35158774, 2022). "However, normal cancer cells may not be directly affected by MSI-1 loss, but rather indirectly by loss of cancer stem cells in the tumor environment." (PMID 34291358, 2021). "Enforced expression of GATA3 in HCT116 cells inhibited a series of cancer-promoting proteins, DNMT1, SETD1A, SETDB1, FOXM1, MYC, and MSI1." (PMID 34595169, 2021). "Compared with monolayer-culture GBM cell lines, cancer stem cell (CSC) markers such as SOX2, PROM1, POU5F1, MSI1, FUT4, and CXCR4 were upregulated in the spheroids." (PMID 34638384, 2021). "The conserved pro-oncogenic potential of oncofetal RBPs (oncoRBPs), such as MSI1 or IGF2BP1, suggests these as candidate targets in cancer treatment." (PMID 33291443, 2020). "MSI1 was shown to be a direct translational activator of ICAM1, a cell surface protein directly involved in cancer cell migration." (PMID 33317545, 2020). "Therefore, it could be concluded that the overexpression of MSI1 enhances cancer promotion." (PMID 32448364, 2020). "By ectopic expression of MSI1 in NSCLC cell lines, A549 and H522, phosphorylated Akt is increased and cancer cell proliferation is elevated." (PMID 32448364, 2020). "Extensive genes have been identified as the target of miR-761 in numerous cancers, including HDAC1, Rab3D, Runx3, Mitofusin-2, CXCR1, TRIM29, MSI1, ING4, TIMP2, and GSK3β." (PMID 32185226, 2020). "MSI1 and MSI2 share similar roles in stem cells and in cancer initiation and progression, but they also have distinct roles." (PMID 32784494, 2020). "By coordinating the two mechanisms, MSI1/AGO2 complex enhances tumor proliferation and ensures cancer cell survival under hypoxia or chemodrug treatment." (PMID 31903115, 2020). "One such group of RBPs, Musashi proteins comprised of MSI1 and MSI2, has been long studied in neurogenesis and cancer biology." (PMID 30367664, 2018). "Our goal is to develop potent and specific MSI1/MSI2 inhibitors, and ultimately move these new inhibitors into clinical applications in the treatment of cancers with MSI overexpression." (PMID 30097032, 2018).
cancer (continued). "Quantitative PCR analyses were performed to measure the transcriptional regulation of cancer stemness markers, such as ALDH-1, CD133, CD44, Lgr-5, Msi-1, EphR1, and Bmi-1, by BP compounds." (PMID 28862656, 2017). "Each BP compound induced the expression of certain cancer stemness markers.1-BP strongly induced the expression of ALDH-1, CD133, Lgr-5, and Msi-1, but had little effect on CD44." (PMID 28862656, 2017). "Thus our data suggested that Msi1 may promote cancer cell proliferation." (PMID 18826648, 2008). "Musashi‐1 (MSI1) and Musashi‐2 (MSI2) are highly expressed in various cancers." (PMID 40761481, 2025). "Calcitriol increases the expression of stemness-related genes, such as the leucine-rich repeat-containing G protein-coupled receptor 5 (LGR5), SMOC2, LRIG1, MEX3A, MSI1, and PTK7, attenuating the transformation into cancer stem cells, and, therefore, impacts tumorigenesis at a very early stage." (PMID 36364774, 2022). "Nonetheless, there is currently no study that strategizes MSI1 as a therapeutic target against any cancer types." (PMID 35158774, 2022). "In OV, MSI1 acted as an oncogene, inducing phosphorylation of ERK protein, activating the expression of anti-apoptotic protein Bcl-2, and promoting migration and invasion of cancer cells." (PMID 35980273, 2022). "Msi1 activated Notch signaling not only by translationally inhibiting NUMB, but also by downregulating the 26S proteasome by binding to the mRNA of NF-YA in cancer stem cells (CSCs) or tumor-initiating cells." (PMID 33758618, 2021). "Silencing of MSI1 by shRNA in MSI1-high-expressing radioresistant GBM cell line.Generation of mouse xenograft tumors with GMB cancer cells lacking MSI1." (PMID 34900673, 2021). "Musashi 1 (MSI1) is a member of Musashi family and can be regulated by miRNA in cancer progression." (PMID 33882945, 2021). "In contrast, barely any conservation was seen among genes with inverse expression to MSI1 in cancer (data not shown)." (PMID 34062997, 2021). "Furthermore, the overexpression of MSI1, a stem-like marker, promoted an increase in survival, invasion, EMT-like phenotype, and maintenance of cancer stem properties after radiation, through hyperactivation of DDR and DNA repair by HR." (PMID 34900673, 2021). "MSI1 promotes self-renewal and impairs differentiation in cancer and non-malignant progenitor cells." (PMID 33291443, 2020). "However, PI3K inhibitors including A66 and BEZ235 are observed to increase the expression of cancer stem cell (CSC) genes (SOX2, OCT4 and MSI1) in GBM CSC models, which exhibit therapy resistance." (PMID 32333246, 2020). "Our studies indicate that MSI1 is a potent and druggable enhancer of CSC marker expression and properties in GBM, strongly emphasizing to expedite clinical evaluation and improvement of MSI1-directed inhibitors for cancer treatment." (PMID 33291443, 2020). "MSI1 and MSI2 can positively or negatively regulate mRNA translation in cancer." (PMID 32967226, 2020). "Moreover, we found that hypoxic stress significantly enhanced the recruitment of AGO2 to cytosolic MSI1 in GBM and PDAC cancer cells." (PMID 31903115, 2020). "Musashi 1 (MSI1) and MSI2 have been shown to increase the levels of Myc and estrogen receptor α1 (ESR1) oncogenes and reduce that of phosphatase and tensin homlog (PTEN) by modulating mRNA stability and protein translation, leading to various types of cancer." (PMID 33193718, 2020). "Some studies demonstrated that MSI1 enhances epithelial cell growth by promoting canonical Wnt signaling pathway, which is consistent with our findings that NANOGP8 raises β-catenin accumulation in cancer cell nucleus." (PMID 29689047, 2018). "The defect observed in sphere formation was more severe in subsequent serial passages (data not shown), thus indicating a role for Msi1 in sustaining cancer cells." (PMID 18826648, 2008).